PARN (poly(A)-specific ribonuclease)
Diseases named in the same sentence as PARN in open-access papers (continued):
Sharing a sentence is not in itself a finding about the gene and the disease.
cancer (15 papers, 2012 to 2024). A tumor composed of atypical neoplastic, often pleomorphic cells that invade other tissues. "It was shown that PARN targets a discrete set of mRNAs in mouse fibroblasts, many of which encode for the factors required in cell migration and adhesion, while analogous observations are reported in cell lines of cancer origin." (PMID 35630580, 2022). "Furthermore, CNOT6L and PARN deadenylases are linked to the expression of cancer-related mRNAs." (PMID 26541675, 2015). "Lastly, we determined that a group of genes with reported connections to cancer and/or AD are regulated by PARN, Pin1 and tau, further supporting the idea of the functional interactions of these factors." (PMID 31749682, 2019). "hTERC alterations in cancer: Recent work has proposed that hTERC maturation involves the poly(A)-specific ribonuclease (PARN) which is localized in the nucleolus and in the Cajal body (CB)." (PMID 31157162, 2019). "Silencing of PARN in another cancer cell line, Hep2, affected a different population and revealed very few common genes as compared to NCI-H520, suggesting that the effects are SCC-specific." (PMID 26541675, 2015). "Although the complete structure of the full-length human PARN, as well as several aspects of the catalytic mechanism still remain elusive, many previous studies indicate that PARN can be used as potent and promising anti-cancer target." (PMID 23236441, 2012). "Moreover, PARN expression is de-regulated in many cancers, including solid tumours and hematopoietic malignancies." (PMID 37340076, 2023). "The discovery and development of a selective and effective PARN inhibitor could be a useful tool for cancer treatment." (PMID 37002320, 2023). "Recently, only PARN has been proposed as a potential target of experimental cancer treatment." (PMID 35565367, 2022). "The importance of PARN in cell cycle progression has been revealed by its essential role during early development in both vertebrates and higher plants and the proliferation of several types of cancer cells." (PMID 31936572, 2020). "Tau, Pin1 and PARN target the expression of mRNAs deregulated in AD and/or cancer." (PMID 31749682, 2019). "Interestingly, the expression of a group of mRNAs deregulated in AD and/or cancer are targeted by Pin1, tau and PARN, further supporting overlapping functions for these factors in the nucleus." (PMID 31749682, 2019). "Collectively, these findings indicate that pharmacological and clinical approaches targeting single or multiple relevant components of the uninvestigated miRNA-modulatory network of PARN could be utilized to develop effective and precise cancer treatments to impede disease progression." (PMID 38689093, 2024). "Interestingly, PARN expression is altered in different cancers." (PMID 26400160, 2015). "Further, we silenced the expression of PARN and NOC and we identified transcripts and gene ontologies (GO) affected by these deadenylases in two cell lines of different cancer origin." (PMID 26541675, 2015).
cancer (continued). "In this work, we silenced PARN and NOC in NCI-H520 and Hep2 cancer cells to identify changes in gene expression, possibly related to the altered expression of the enzymes that we observed in SCC samples." (PMID 26541675, 2015). "Among these, poly(A)-specific ribonuclease (PARN) has been involved in key biological processes, such as development, cell cycle progression, DNA damage response and cancer." (PMID 23236441, 2012). "We also present evidence that PLD2/PA regulates PARN expression and that PARN also in turn regulates PLD2 transcript levels in a negative feedback loop that is deregulated in cancer cells." (PMID 28011629, 2017). "In conclusion, we report here a regulatory relationship between PARN and PLD2/PA, which constitutes a new and possibly essential component in post-transcriptional regulation in higher eukaryotes, as well as in disease states such as cancer." (PMID 28011629, 2017). "Since PLD2 levels are naturally high in cancer cells, our results indicate that either PARN is deregulated in cancer cells, not allowing inhibition of PLD2 expression, or that PLD2 activity contributes to increased mRNA stabilization, or both." (PMID 28011629, 2017). "However, PARN did affect invasion and showed differential effects on cell motility when compared to the study of Lee and coworkers on mouse myoblasts, leading to the suggestion that cancer cells may utilize different regulatory mechanisms of cell motility from mouse myoblasts." (PMID 26541675, 2015). "Moreover, the silencing of PARN and NOC in two cell lines of different cancer origin, NCI-H520 and Hep2, affected different groups of transcripts with very few genes in common, suggesting a discrete role for each enzyme in different cancer types." (PMID 26541675, 2015). "PARN, a major deadenylase in mammalian cells, can potentially act as a tumor suppressor, given that it is activated by the tumor-suppressor BARD1 and it is involved in the degradation of IL-8, VEGF, c-jun, uPA, c-fos and TNF-alpha mRNAs, the levels of which are generally increased in cancers." (PMID 26541675, 2015). "Regarding the levels of deadenylases in cancer, it is shown that in acute types of leukemia (AML, ALL), the levels of both PARN and CNOT6 increase compared to non-malignant clinical samples, while the opposite is the case for CNOT6L and CNOT7." (PMID 35630580, 2022).
genetic disease (3 papers, 2019 to 2022). "PARN loss-of-function mutations result in a severe form of hereditary disease, and previous research indicated that PARN deficiency affects not only the stability of noncoding RNAs, such as human telomerase RNA, but also the levels of several miRNAs in human cells." (PMID 35740302, 2022). "Mutations in PARN, dyskerin or NOP10 cause severe genetic disorders, emphasizing the functional significance of these telomerase subunits and RNA maturation mechanisms." (PMID 33095156, 2020). "Sequencing analysis in a recent P1's blood sample did not reveal any somatic genetic modification in PARN (data not shown), ruling out the possibility of a spontaneous genetic reversion or correction as reported in other hematologic genetic disease." (PMID 31273937, 2019).
hematologic malignancies (2 papers, 2020 to 2025). "Heterozygous PARN variant carriers were reported in association with blood count abnormalities but without hematological malignancies." (PMID 39940930, 2025).
neurological disorders (1 paper, 2019).
renal disease (1 paper, 2020). "Furthermore, several VUS in known renal disease genes were analyzed by means of retrospective phenotyping or upon complementary DNA (cDNA)-based splice site analysis (GANAB: c.2319G>A, p.Ala773=, PARN: c.1405+3A>G in ID52.1, SEC63: c.1936–8->TTT in ID20.1 and ID97.1), disproving pathogenicity." (PMID 32398770, 2020).
PARN also shares sentences with these, for which no sentence is quoted: tumor (5 papers); bone marrow failure (3); acute myeloid leukemia (1); ankylosing spondylitis (1); CHARGE syndrome (1); Dent disease (1); Evans syndrome (1); gastric tumor (1); leukemia (1); leukopenia (1); myeloid malignancies (1); neutropenia (1); poikiloderma with neutropenia (1); pontocerebellar hypoplasia (1); pulmonary disease (1); small cell lung carcinoma (1); systemic sclerosis (1); ulcerative colitis (1).